GJD4 (gap junction protein delta 4)
Description:
One gap junction consists of a cluster of closely packed pairs of transmembrane channels, the connexons, through which materials of low MW diffuse from one cell to a neighboring cell.
Synonyms: Cx40.1; FLJ90023
Tractability: Small molecule: a structure with a bound ligand is known. Antibody: UniProt places it where antibodies can reach, with medium confidence; UniProt predicts a signal peptide or a membrane-spanning region; its Gene Ontology location is reachable by antibodies, with medium confidence.
Gene: Protein-coding gene on chromosome 10 (35,605,341 to 35,608,935, forward strand). Ensembl gene ENSG00000177291.
Subcellular location: Cell membrane; Cell junction, gap junction
Pathways (Reactome):
Vesicle-mediated transport: Gap junction assembly
Gene Ontology:
Molecular function: protein binding; gap junction channel activity
Biological process: cell-cell signaling; cell communication; transmembrane transport
Cellular component: connexin complex; gap junction; plasma membrane
Genetic constraint (gnomAD): Loss-of-function variants: 16 observed, 12.15 expected, observed/expected ratio (o/e) 1.32, 90% interval 0.88 to 1.85. The synonymous counts are far from expectation, so gnomAD's model fits this gene poorly and the ratio says little. Missense variants: 613 observed, 430.76 expected, observed/expected ratio (o/e) 1.42, 90% interval 1.33 to 1.52. Synonymous variants: 285 observed, 210.33 expected, observed/expected ratio (o/e) 1.36, 90% interval 1.23 to 1.5.
Homologues: Orthologues: chimpanzee GJD4 (96% identical), macaque GJD4 (93% identical), rabbit GJD4 (56% identical), guinea pig GJD4 (54% identical), mouse Gjd4 (50% identical), rat Gjd4 (49% identical), tropical clawed frog gjd4 (38% identical), dog GJD4 (34% identical). Paralogues in human: GJC2 (26% identical), GJA8 (24% identical), GJC1 (24% identical), GJD3 (24% identical), GJA10 (24% identical), GJA5 (23% identical), GJA3 (22% identical), GJA4 (22% identical), GJA9 (22% identical), GJD2 (21% identical), GJA1 (21% identical), GJB1 (21% identical), and 8 more.
Diseases named in the same sentence as GJD4 in open-access papers:
GJD4 is named in the same sentence as 1 disease in open-access papers, as found by Europe PMC text mining. Sharing a sentence is not in itself a finding about the gene and the disease.
GJD4 shares sentences with these, for which no sentence is quoted: dysferlinopathy (1 paper).